LZTR1 (leucine zipper like post translational regulator 1)
Diseases named in the same sentence as LZTR1 in open-access papers (continued):
Sharing a sentence is not in itself a finding about the gene and the disease.
glioblastoma (13 papers, 2017 to 2025). The most malignant astrocytic tumor (WHO grade IV). "Some studies have found that somatic and germline mutations in LZTR1 were associated with glioblastoma multiforme and multiple schwannomas." (PMID 35770001, 2022). "Introducing LZTR1 to LZTR1-mutated glioblastoma cells decreases cyclin A and polo-like kinase 1 expression, indicating the importance of LZTR1 in cell cycle progression." (PMID 34604034, 2021). "Several studies have revealed the tumor-suppressive role of LZTR1, and the germline and somatic mutations of LZTR1 in patients with glioblastoma and schwannomatosis." (PMID 33028809, 2020). "Somatic mutations in LZTR1 occur in 22% of glioblastomas and in several other cancers according to the Catalogue of Somatic Mutations in Cancer (COSMIC) database." (PMID 27921248, 2017). "Loss of function mutations in the LZTR1 gene were described in one-fifth of glioblastoma cases." (PMID 40724954, 2025). "Additionally, rare variants of LZTR1 were confirmed for different cancer types (glioblastoma, hepatocellular, esophagogastric, colorectal, and lung cancers), including breast cancer." (PMID 40724954, 2025). "Mutations in LZTR1 also occur in several cancer types, including ~22% glioblastomas." (PMID 34604034, 2021). "LZTR1 is a gene normally expressed in the brain and encodes a protein acting as an adaptor of cullin 3 ubiquitin ligase; this gene was found to be deleted and mutated in about 22% and 4.5%, of glioblastomas, respectively." (PMID 30279357, 2018). "Glioblastoma tumors with a LZTR1 deletion displayed enrichment for genes associated with the proliferation of glioma stem cells; in line with this observation, enforced expression of LZTR1 into glioblastoma cancer stem cells inhibited tumor-sphere formation." (PMID 30279357, 2018). "Moreover, somatic loss-of-function mutations in LZTR1 occur in 22% of glioblastomas." (PMID 35197475, 2022). "LZTR1 acts as a tumor suppressor gene; for instance, somatic loss-of-function (LOF) variants in LZTR1 occur in 22% of glioblastomas (high-grade astrocytic neoplasms)." (PMID 39062695, 2024). "Though the mechanism has yet to be elucidated in sarcomas, mutations or deletions of LZTR1 disrupt RAS regulations by LZTR1-mediated ubiquitination and allow glioblastoma to retain its proliferative features." (PMID 34659131, 2021). "The biallelic inactivation of LZTR1 in glioblastomas, and the observation that LZTR1 inactivation drives self-renewal and growth of glioma spheres, are indicative of LZTR1 acting as a classic tumour suppressor gene." (PMID 27921248, 2017).
Vestibular schwannoma (9 papers, 2017 to 2025). A vestibular schwannoma (also known as acoustic neuroma, acoustic neurinoma, or acoustic neurilemoma) is a benign, usually slow-growing tumor that develops from the VIIIth cranial nerve supplying the inner ear. "So far, only one patient with a germline pathogenic LZTR1 variant has been reported with bilateral vestibular schwannoma." (PMID 40794298, 2025). "This included 4/110 patients who presented with sporadic vestibular schwannoma who were screened for LZTR1 variants." (PMID 33879870, 2021). "Furthermore, LZTR1 germline pathogenic variants have been recently associated with higher risk of Unilateral Vestibular Schwannomas." (PMID 35361920, 2022). "This is because unilateral vestibular schwannomas may occur in patients with mosaic NF2-related SWN but also in patients with germline LZTR1 PVs." (PMID 40794298, 2025). "Three genes centromeric to NF2 on 22q have now been found shown to account for ~ 70% of familial and ~ 30% of sporadic patients with multiple non-vestibular schwannomas: SMARCB1, LZTR1, and much less commonly DGCR8." (PMID 41160189, 2025). "In contrast, vestibular schwannomas have not been definitively associated with SMARCB1-SWN, but have been observed in approximately 5% of LZTR1-SWN." (PMID 41284083, 2025).
glioma (8 papers, 2017 to 2022). A benign or malignant brain and spinal cord tumor that arises from glial cells (astrocytes, oligodendrocytes, ependymal cells). "LZTR1 is also thought to be a tumor suppressor as loss-of-function mutations have been associated with schwannomatosis and glioma." (PMID 34222248, 2021). "Indeed, several of the R-loop-forming genes we identified in NSPCs show rearrangements and mutations in human low-grade and high-grade gliomas, including Raf1, Daxx, Fgfr1, Lztr1, and H3F3A 46–48, which warrants further studies of the role of R-loops in brain cancer development." (PMID 35927309, 2022). "LZTR1 mutations identified in GB cluster on critical substrate recognition residues within the kelch domain and GB tumours that bear LZTR1 mutations have a gene expression profile enriched for genes previously associated with glioma growth and neurosphere formation." (PMID 33432111, 2021). "Pathogenic LZTR1 germline variants have been reported in children with different cancer types, including high-grade glioma, but have not been evaluated in the majority of the existing large pan-childhood cancer germline sequencing studies." (PMID 36008825, 2022). "Increasing genetic evidence in 22q11.2 deletion syndrome, NS, and glioma tumors point toward the negative health impact of Lztr1 mutation or deletion in multiple organ systems, including the brain." (PMID 34222248, 2021).
neurofibromatosis (7 papers, 2019 to 2025). A hereditary neoplastic syndrome in which tumors grow in the nervous system. "Germline loss of LZTR1, leucine-zipper-like transcriptional regulator 1, is a cause of a type of neurofibromatosis, like NF2." (PMID 33556121, 2021). "On the other hand, little is known about the function of LZTR1, except that its loss has been associated with neurofibromatosis." (PMID 32339168, 2020). "Nf1 is another important regulator of Ras signaling, and mutations in Nf1 and LZTR1 both give rise to types of neurofibromatosis." (PMID 32339168, 2020).
meningioma (6 papers, 2017 to 2025). A generally slow growing tumor attached to the dura mater. "Meningiomas occur with greater frequency in patients with germline mutations of genes such as type-2 neurofibromatosis (NF2), type-1 neurofibromatosis (NF1, 19–24% of adolescent meningiomas), type-1 multiple endocrine neoplasia (MEN1), SMARCB1, LZTR1, or SMARCE1 genes." (PMID 37760490, 2023).
melanoma (5 papers, 2022 to 2025). A malignant, usually aggressive tumor composed of atypical, neoplastic melanocytes. "The results show that LZTR1 regulates the ubiquitin proteasome system in melanoma cells and also associates with actin-related proteins and actin cytoskeleton organization." (PMID 40885854, 2025). "LZTR1 is a "safeguard" for melanoma cells under stress and its downregulation can be exploited for melanoma therapy." (PMID 40885854, 2025). "In doing so, we identified six genes, including LZTR1 (leucine zipper-like transcription regulator 1), which exhibited the greatest copy number change across acral melanoma specimens, on average (bottom)." (PMID 35197475, 2022). "To this end, we performed bulk RNA sequencing of a melanoma cell line (YUSIK) to assess the impact of LZTR1 knockdown." (PMID 35197475, 2022). "The ability of LZTR1 to convert immortalized mouse melanocytes to a growth-factor independent mode of proliferation, a major characteristic of melanoma cells in culture, further underscores its tumorigenic potential." (PMID 35197475, 2022). "Remarkably, depletion of LZTR1 induced transcriptome-wide changes that largely mirrored those observed in bulk tumors and single melanoma cells." (PMID 35197475, 2022). "Nevertheless, we found that high expression of LZTR1 is predictive of poor outcome, both in acral and sun-exposed melanomas from this study, and in 443 advanced sun-exposed melanomas profiled by TCGA (The Cancer Genome Atlas)." (PMID 35197475, 2022). "Indeed, suppression of LZTR1 in melanoma cells increased the constitutive levels of GTP-bound RAS, an effect similar to that observed in growth factor-stimulated cells." (PMID 35197475, 2022). "Silencing of LZTR1 in melanoma cell lines causes apoptotic cell death independent of major hotspot mutations or melanoma subtypes." (PMID 35197475, 2022). "However, only LZTR1 released immortalized mouse melanocytes from their dependency on growth factors, a characteristic shared by melanoma cells." (PMID 35197475, 2022). "LZTR1 is co-amplified with CRKL and downregulation of each gene inhibits melanoma cell proliferation, albeit to varying degrees." (PMID 35197475, 2022). "In summary, our meta-analyses of 147 acral and 93 mucosal melanomas identified PTPRJ, FER, SKP2, LZTR1, CIC, and PRKN as part of a long tail of driver events that deserves further study and characterization." (PMID 35706047, 2022). "Leucine zipper like transcription regulator 1 (LZTR1) is amplified in acral melanomas, is required for melanocytes and melanoma cell proliferation, and it induces anchorage-independent growth, by yet unknown mechanisms." (PMID 40885854, 2025).
breast carcinoma (4 papers, 2020 to 2025). "The significance of LZTR1 mutation in breast cancer susceptibility was confirmed in exome sequencing metanalysis." (PMID 40724954, 2025). "Increased risk of breast cancer was confirmed for LZTR1 and four other genes, classified as tumor suppressor genes." (PMID 40724954, 2025). "TCGA and related datasets could be used to support the investigation of LZTR1 mutation frequency in breast cancer patients." (PMID 40724954, 2025). "Moreover, LZTR1 has been recently reported in association with congenital malformations, particularly bladder exstrophy and mitral valve prolapse, as well as cancers, including breast cancer, ependymoma, and leukemia." (PMID 39062695, 2024). "In the Gen2Phenotype database, information about LZTR1 involvement in hereditary breast carcinoma is described (ID: G2P03479)." (PMID 40724954, 2025). "The four TSGs: CBLC, CDH11, LZTR1, and TET2 previously shown to be most frequently mutated in 1KGP were also observed to display changes in ASE in breast cancer." (PMID 32064050, 2020). "However, LZTR1 expression on a transcriptomic level was confirmed in patients (both sexes) with breast cancer, but its status was described as not significant in disease pathogenesis because of its insignificant frequency in the study population." (PMID 40724954, 2025).
DiGeorge Syndromes (4 papers, 2020 to 2024). "LZTR1 is a human disease gene associated with NS and also deleted in some cases of 22q11.2 deletion syndrome." (PMID 34222248, 2021). "LZTR1 mutations are associated with NS and 22q11.2 deletion syndrome, both of which show a variety of phenotypes, including neurological dysfunction." (PMID 34222248, 2021). "LZTR1 was originally identified as one of the candidate genes deleted in some 22q11.2 deletion syndrome patients." (PMID 34222248, 2021). "LZTR1 encodes a member of the BTB-Kelch superfamily that is highly expressed in the heart during development and has been associated with Noonan and DiGeorge Syndromes, both of which are characterized by CHD." (PMID 32349777, 2020).
ependymoma (4 papers, 2021 to 2025). A WHO grade II, slow growing tumor of children and young adults, usually located intraventricularly. "Of note, the only other LZTR1 variant observed in our cohort was a VUS (p.Asp703Asn [c.2107G > A]) in another child diagnosed with the same molecular ependymoma subclass (PF-EPN-A1c) in the same location." (PMID 36008825, 2022). "We therefore speculate that pathogenic germline LZTR1 variants may play a role in tumorigenesis for a limited subset of children with ependymoma, perhaps restricted to the PF-EPN-A1c molecular subtype." (PMID 36008825, 2022). "Additionally, LZTR1 is suggested as a novel putative ependymoma predisposition gene." (PMID 36008825, 2022). "In addition, we present LZTR1 as a novel putative ependymoma predisposition gene." (PMID 36008825, 2022). "Upon review of LZTR1 findings in our childhood (non-ependymoma) cancer control cohort, the LZTR1 missense VUS (p.Asp703Asn [c.2107G > A]) detected in another patient with PF-EPN-A1c was observed in a child with acute myeloid leukemia." (PMID 36008825, 2022). "Pathogenic germline variants in LZTR1 have not previously been reported in patients with ependymoma." (PMID 36008825, 2022). "A likely pathogenic LZTR1 variant (p.Gln762Ter [c.2284C > T]), undetected among > 125,000 healthy adult in gnomAD, was found in a child diagnosed with a fourth ventricle PF-EPN-A1c ependymoma." (PMID 36008825, 2022).
pancreatic cancer (4 papers, 2017 to 2026). "The data shows that GSK-3β inhibits LZTR1, leading to a sustained level of K-ras and increased proliferation of the pancreatic cancer cells." (PMID 36430630, 2022). "We next directly examined the roles of LZTR1 and PPP1R2/PP1C in regulating KRAS stability across the tested adenocarcinoma lines, as well as in the pancreatic cancer line Mia PaCa-2." (PMID 41542462, 2026).
acral melanomas (3 papers, 2022 to 2025). "Our findings reveal molecular insights of acral melanoma pathogenesis and designate LZTR1 as a therapeutic target." (PMID 35197475, 2022). "Our results provide insights into the etiology of acral melanoma and implicate LZTR1 as a key tumor promoter and therapeutic target." (PMID 35197475, 2022). "Importantly, our study demonstrates that LZTR1 and CRKL—two of the top genes associated with 22q11.21 amplification in acral melanoma—facilitate anchorage-independent growth in normal human melanocytes, likely by reducing E-cadherin, increasing N-cadherin, and activating integrin β1." (PMID 35197475, 2022).
cardiac hypertrophy (3 papers, 2022 to 2025). "High expression of the RAS subfamily proteins and activation of the MAPK signaling pathway cause cardiac hypertrophy in LZTR1-mutant mice." (PMID 39352760, 2024). "In this study, we demonstrate that a heterozygous AD mutation in LZTR1 caused NS-like phenotypes, including cardiac hypertrophy, low birth weight, short birth stature, and a distinctive facial appearance using AD mutation knock-in mouse models, such as Lztr1R409C/+ and Lztr1G245R/+ mice." (PMID 39352760, 2024). "Additionally, iPSC-CMs from NS patients with LZTR1 alterations are larger than iPSC-CMs from unaffected individuals, suggesting that the cardiac hypertrophy observed in LZTR1-associated NS is linked to increased cardiomyocyte size." (PMID 35178568, 2022). "Alliancegenome showed for Lztr1 Mus musculus gene phenotypes related with abnormal cranium and facile morphology, abnormal heart echocardiography, cardiac hypertrophy, increased cell proliferation, and premature death." (PMID 40724954, 2025). "In this study, we demonstrated that a heterozygous AD mutation in LZTR1 activates MAPK signaling and that trametinib treatment ameliorates cardiac hypertrophy in Lztr1R409C/+ mice." (PMID 39352760, 2024). "LZTR1-mutant male mice exhibit low birth weight, distinctive facial features, and cardiac hypertrophy." (PMID 39352760, 2024). "This was supported by our observation that haploinsufficient mice (Lztr1+/–) did not exhibit any significant phenotypes, whereas heterozygous AD mutations caused cardiac hypertrophy and other phenotypes." (PMID 39352760, 2024). "Conversely, the mTOR signaling pathway was suppressed in Lztr1R409C/+ mice, and rapamycin treatment did not rescue LZTR1 mutation–dependent cardiac hypertrophy." (PMID 39352760, 2024). "Intriguingly, homozygous Lztr1-deficient mice (Lztr1–/–) exhibit embryonic lethality, whereas heterozygous Lztr1-deficient mice (Lztr1+/–) exhibit mild or no specific phenotypes, including cardiac hypertrophy and facial appearance." (PMID 39352760, 2024). "A group reported that Lztr1–/– C57BL/6 mice showed embryonic lethality, whereas Lztr1+/– C57BL/6 mice are born yet show cardiac hypertrophy." (PMID 39352760, 2024). "In contrast, another group demonstrated that Lztr1+/– C57BL/6 mice did not display any specific phenotypes related to heart frailty; however, Lztr1–/– 129S1/SvImJ mice (129 mice) are viable yet show cardiac hypertrophy and facial disability similar to those in patients with NS." (PMID 39352760, 2024).
heart defects (3 papers, 2020 to 2024). "Among these, FBN1 and LZTR1 are well-known risk genes implicated with syndromes that include heart defects." (PMID 32349777, 2020).
hypertrophic cardiomyopathy (3 papers, 2024 to 2025). A condition in which the myocardium is hypertrophied without an obvious cause. "Loss-of-function variants in LZTR1 likely remove a critical checkpoint in this pathway, contributing to a spectrum of features including mild dysmorphisms and cardiac anomalies, although with a reduced prevalence of hypertrophic cardiomyopathy compared to RAF1 or PTPN11." (PMID 40332000, 2025).
neurofibroma (3 papers, 2019 to 2023). An intraneural or extraneural neoplasm arising from nerve tissues and neural sheaths. "Additional recurrent but low-frequency mutations in neurofibromas include FANCA, PTPRD, NF2, LZTR1, KNL1 and RUNX1." (PMID 37164978, 2023).
Noonan syndrome 10 (3 papers, 2019 to 2025). Any Noonan syndrome in which the cause of the disease is a mutation in the LZTR1 gene. "The LZTR1 gene, which encodes a Golgi-localized BTB-Kelch superfamily protein critical for RAS/MAPK pathway regulation, has been definitively linked to Noonan syndrome type 10 (NS10) through gain-of-function variants that drive constitutive pathway activation." (PMID 40646478, 2025).
Obesity (3 papers, 2020 to 2025). Accumulation of substantial excess body fat. "Furthermore, our results show increased adiposity associated with loss of nowl in flies, suggesting that LZTR1 loss may contribute to the increased genetic susceptibility to develop obesity found in human 22q11.2 carriers." (PMID 32339168, 2020).
acute myeloid leukemia (2 papers, 2022). Acute myeloid leukemia (AML) is a group of neoplasms arising from precursor cells committed to the myeloid cell-line differentiation. "In a study on acute myeloid leukemia (AML) cells, the results of genome-wide CRISPR/Cas9 screens revealed negative regulators of the MAPK and mTORC1 signaling pathways, including LZTR1, NF1, and TSC1 or TSC2, were associated with sorafenib resistance." (PMID 35715750, 2022).
bladder exstrophy (2 papers, 2019 to 2024). Bladder exstrophy (or classic bladder exstrophy; CEB) is a congenital genitourinary malformation belonging to the spectrum of the exstrophy-epispadias complex (EEC) and is characterized by an evaginated bladder plate, epispadias and an anterior defect of the pelvis, pelvic floor and abdominal wall. "A heterozygous missense variant in the LZTR1 gene (NM_006767.3, c.2093C>T, p.Ser698Phe, rs760064852) was identified in one individual with isolated bladder exstrophy." (PMID 31044557, 2019).
bleeding disorders (2 papers, 2021 to 2022). "Considering that bleeding disorders have been described in patients with mutations in both these genes, the absence of LZTR1 and RAF1 mutations in our patients is very likely related to the limited size of the study cohort rather than to specific genotype–phenotype correlations." (PMID 34857025, 2021).
chronic myeloid leukemia (2 papers, 2019 to 2021). "For instance, in a drug resistant model of chronic myeloid leukemia, cullin-based ubiquitin ligase 3 (CUL3)/leucine zipper-like transcription regulator 1 (LZTR1) complex inhibition leads to increased MAPK signaling and reduced sensitivity to chemotherapy." (PMID 31739603, 2019).
developmental delay (2 papers, 2025). "Moreover, LZTR1 variant has been previously reported to be associated with severe developmental delay and intellectual disability, both of which were absent in this case, supporting a broader phenotypic spectrum or variable expressivity." (PMID 41292581, 2025).